RUNX1 (RUNX family transcription factor 1)
Diseases named in the same sentence as RUNX1 in open-access papers (continued):
Sharing a sentence is not in itself a finding about the gene and the disease.
acute lymphoblastic leukemia (144 papers, 2005 to 2026). Leukemia with an acute onset, characterized by the presence of lymphoblasts in the bone marrow and the peripheral blood. "Among the pediatric/AYA cohort, the ETV6::RUNX1 fusion typically associated with a favorable outcome in acute lymphoblastic leukemia was most frequent." (PMID 37686670, 2023). "More recently, whole genome sequencing studies of acute lymphoblastic leukemia (ALL) patients carrying the ETV6/RUNX1 translocation have further implicated broken RSSs in the generation of chromosome alterations." (PMID 30905508, 2019). "RUNX1 is the most frequent target for chromosomal translocation in AML, and RUNX1 point mutations are found in hematological diseases such as AML as well as acute lymphocytic leukemia (ALL)." (PMID 26512706, 2015). "While ETV6::RUNX1-positive acute lymphoblastic leukemia (ALL) is generally associated with favorable outcomes, a subset of patients experience relapse despite receiving standard therapy, underscoring the need for early biomarkers to identify high-risk subgroups." (PMID 42213136, 2026). "Two of the genes associated with the MMR pathway, MSH6 and SETD2, were among the genes found to be frequently mutated in relapsed or therapy resistant ETV6/RUNX1 acute lymphoblastic leukemia (ALL)." (PMID 36672189, 2023). "Mono-allelic RUNX1 mutations occur in approximately 15% of T-Cell Acute Lymphoblastic Leukemia (T-ALL), predominantly in cases with an immature phenotype and a poor prognosis." (PMID 32572036, 2020). "To compare the mouse model results to the situation in Acute Lymphoblastic Leukemia (ALL) we analyzed TCRβ gene rearrangements in T-ALL samples harboring heterozygous Runx1 mutations." (PMID 32572036, 2020). "We observed co-immunoprecipitation of PTBP1 and RUNX1 in all the cell lines tested, indicating that the interaction between PTBP1 and RUNX1 is present in both myeloid and lymphoblastic leukemia cells." (PMID 41214140, 2026). "Several other recurrent alterations, such as ETV6::RUNX1, KMT2A rearrangements, and high hyperdiploidy in childhood acute lymphoblastic leukemia, are associated with prognosis and treatment decisions." (PMID 40725438, 2025). "Further in 2019, METTL3 and METTL14 expression was reported to be downregulated in ETV6/RUNX1-positive acute lymphoblastic leukemia as compared to the controls." (PMID 39600630, 2024). "Interestingly, recent evidence indicates germline mutations in RUNX1 are associated with an increased risk of acute lymphoblastic leukemia (ALL) and that these mutations result in the generation of dominant negative isoforms of RUNX1." (PMID 35241129, 2022). "ETV6::RUNX1 is a genetic rearrangement of good prognosis in children with acute lymphoblastic leukemia (ALL)." (PMID 35685921, 2022). "METTL3 and METTL14 expression was reported to be downregulated in pediatric acute lymphoblastic leukemia (ALL) with ETV6/RUNX1 gene rearrangement." (PMID 33922187, 2021). "Acute Lymphoblastic Leukaemia (ALL) with the ETV6/RUNX1 fusion gene is the most common malignant disorder found in children." (PMID 33292265, 2020). "This study was aimed to explore the METTL3 and METTL14 expressions in children with ETV6/RUNX1(E/R)‐positive acute lymphoblastic leukemia (ALL) and investigate the relation between the METTL3 and METTL14 expressions with clinical features." (PMID 31429529, 2019). "RUNX1 is a recurrent target of somatic mutations in de novo AML, myelodysplastic syndrome (MDS), acute lymphocytic leukemia (ALL), atypical chronic myeloid leukemia (aCML), and secondary AML." (PMID 29326930, 2017). "The first cluster (cluster 3) is HPC specific and proximal to cluster 4, which contains RUNX1 and T cell acute lymphocytic leukemia 1, the 2 transcription factors indispensable for generating HPCs." (PMID 25717144, 2015).
acute lymphoblastic leukemia (continued). "It is also notable that the clustering of MYB, NOTCH1, RUNX1, and FBXW7 mutations seen in this uncommon epithelial tumor ACC overlaps with frequent somatic mutations seen in human acute lymphocytic leukemia patients." (PMID 25587024, 2014). "The ETV6/RUNX1 (E/R) fusion gene (also known as TEL/AML1) is the hallmark of one of the most common genetic subtypes of B-cell precursor acute lymphoblastic leukemia (BCP ALL) in children." (PMID 22028862, 2011). "ETV6/RUNX1 (E/R) is the most common fusion gene in childhood acute lymphoblastic leukemia (ALL)." (PMID 28418909, 2017). "ETV6/RUNX1 (E/R) is the most common fusion gene in childhood acute lymphoblastic leukemia." (PMID 24240203, 2014). "ETV6::RUNX1 is the second most frequent form of B cell acute lymphoblastic leukemia (B-ALL) in childhood." (PMID 40634509, 2025). "It has been found that PRMT7 regulates the expression of RUNX1 target genes in T cell acute lymphoblastic leukemia (T-ALL) and plays an active role in the pathogenesis of T-ALL." (PMID 41154773, 2025). "The finding that CIC may directly regulate RUNX1, a gene linked to leukaemogenesis, may provide mechanistic insight into the reported associations between CIC loss and altered T‐cell development and T‐cell acute lymphoblastic leukaemia (T‐ALL) onset in mice." (PMID 34767259, 2022). "The ETV6-RUNX1 chimeric- and native RUNX1-responsive regulomes in paediatric B-acute lymphoblastic leukemia (B-ALL) remain to be characterized." (PMID 36411286, 2022). "ETV6/RUNX1 gene fusion is the most common chromosomal translocation abnormality occurred in pediatric B-cell acute lymphoblastic leukemia (B-ALL)." (PMID 34101758, 2021). "RUNX1 mutations have frequently been identified in a variety of hematological malignancies, including AML, MDS, MPN, and acute lymphoblastic leukemia (ALL)." (PMID 33799787, 2021). "Conversely, RUNX1 serves as a key component of the core transcriptional TAL1–GATA3–RUNX1 complex to support the malignant state of human T cell acute lymphoblastic leukemia (T-ALL)." (PMID 34831147, 2021). "A high resolution 244K array-based Comparative Genomic Hybridization (array-CGH) was used to study eleven ETV6/RUNX1-positive childhood acute lymphoblastic leukemia (ALL) patients." (PMID 23151340, 2012). "Approximately 25%–50% of individuals with RUNX1-FPDMM will develop malignancy, mainly MDS and AML and less frequently acute lymphoblastic leukemia (ALL) or lymphoma or other hematologic malignancies." (PMID 41458504, 2025). "In acute lymphoblastic leukemia (ALL), a fusion occurs between the TEL (ETV6) gene (on chromosome 12) and the RUNX1 gene (on chromosome 21), thus upregulating members of the miR-99a/let-7c/miR-125b cluster and miR-100." (PMID 40161350, 2025). "Proband IV‐3, a child diagnosed with B‐acute lymphoblastic leukemia (B‐ALL) at 8 years old, tested positive for ETV6::RUNX1 fusion." (PMID 38970307, 2024). "Recent trials show 5-year survival rates >95% for ETV6::RUNX1 Acute Lymphoblastic Leukemia (ALL)." (PMID 38844578, 2024). "In RUNX1-FPD, cases of secondary malignancy with MDS after therapy for acute lymphoblastic leukemia (ALL) have been described, particularly in survivors of childhood T-cell ALL." (PMID 35356204, 2022). "Noteworthy, acquired mono- or biallelic somatic RUNX1 variants, including deletions, missense, splice site, frameshift, and nonsense variants, correlate with worse prognosis in sporadic AML, MDS, and T-cell acute lymphoblastic leukemia (T-ALL)." (PMID 35884491, 2022). "RUNX1 gene deregulation, either by genetic alterations (point mutation or chromosome abnormalities) or gene expression modification, is involved in many hematological malignancies, notably in ETV6-RUNX1 pre-B acute lymphoblastic leukemia (BCP-ALL)." (PMID 33743795, 2021). "In childhood B-precursor acute lymphoblastic leukemia (B-ALL), the ETV6/RUNX1 fusion transcript is considered to have an excellent outcome." (PMID 30115129, 2018).
acute lymphoblastic leukemia (continued). "Dysregulation of RUNX1 gene also results in development of other hematological disorders such as Myelo Dysplastic Syndrome (MDS), Acute Lymphoblastic Leukemia (ALL) and Familial Platelet Disorder (FPD)." (PMID 26901859, 2016). "Chromosomal translocations involving RUNX1 are found in multiple hematopoietic malignancies including acute myelogenous leukemia (AML), acute lymphocytic leukemia (ALL), and therapy-related AML and myelodysplastic syndrome (MDS)." (PMID 22145044, 2011). "Fourth, we performed a 4-year follow-up in which none of the ETV6::RUNX1-positive newborns have been diagnosed with acute lymphoblastic leukemia." (PMID 40243620, 2025). "A clinical follow-up was conducted on 137 B-ALL children with positive genes (59 cases of ETV6/RUNX1 positivity, 22 cases of E2A/PBX1 positivity, 25 cases of MLL positivity, and 19 cases of BCR/ABL positivity) among 302 children with acute lymphoblastic leukemia." (PMID 41195225, 2025). "ETV6::RUNX1-positive pediatric acute lymphoblastic leukemia frequently has a prenatal origin and follows a two-hit model: a first somatic alteration leads to the formation of the oncogenic fusion gene ETV6::RUNX1 and the generation of a preleukemic clone in utero." (PMID 40243620, 2025). "Current models suggest that RUNX1 cooperates with other oncogenic factors (e.g., NOTCH1, TAL1) to drive the expression of proto-oncogenes in T cell acute lymphoblastic leukemia (T-ALL) but the molecular mechanisms controlled by RUNX1 and its cooperation with other factors remain unclear." (PMID 37213235, 2023). "Also, RUNX1 binds to NFATC2 promotor region in CD4 T cell of mouse and human, and Jurkat T cell acute lymphoblastic leukemia cell line." (PMID 35844683, 2021). "Furthermore, in 5% of children with acute lymphoblastic leukemia (ALL), the t chromosomal translocation specifically targets the E2A gene, resulting in an oncogenic E2A-PBX1 fusion protein and becoming a coactivator for RUNX1, resulting in unfavorable B-cell development." (PMID 37444447, 2023). "Acute lymphoblastic leukemia (ALL) is the most common pediatric hematological malignancy, with ETV6::RUNX1 being the most prevalent translocation whose exact pathogenesis remains unclear." (PMID 37670323, 2023). "In T‐cell acute lymphoblastic leukemia (T‐ALL), specific non‐coding mutations upstream of the TAL1 oncogene are capable of generating a self‐sustaining transcriptional loop, which involves several T‐ALL transcription factors such as MYB, GATA3, RUNX1 and TAL1 itself." (PMID 27756687, 2017).
breast cancer (139 papers, 2007 to 2026). A primary or metastatic malignant neoplasm involving the breast. "Conversely, there is a loss of RUNX1 expression in the development of luminal estrogen-receptor-positive (ER+) breast cancer, pointing to a tumor-suppressive function." (PMID 39309442, 2024). "RUNX1 is one of the genes significantly mutated in luminal estrogen-receptor-positive (ER+) breast cancer." (PMID 38430423, 2024). "Recurrent mutations in the Runt domain of RUNX1 have been identified in acute myeloid leukemia and luminal-type breast cancer." (PMID 36766749, 2023). "Recently, Halperin (2022) reported that RUNX1 expression is upregulated in cancer-associated fibroblasts and that the RUNX1 signature is associated with poor breast cancer outcomes." (PMID 36766786, 2023). "First, in breast cancers, RUNX1 walker domain mutations (G141 and R142 residues) were defective for DNA damage-dependent RUNX PARylation." (PMID 37190015, 2023). "In ER+ breast cancer, somatic mutations such as frame-shift mutations and point mutations, and deletions of RUNX1, have pointed to a tumor suppressive role." (PMID 36831308, 2023). "While RUNX1 and CBFβ have been most widely studied in the context of blood cancers, they have over the last decade been implicated in breast cancers, both in the context of tumor suppression and tumor promotion." (PMID 36831308, 2023). "This was supported by results using the MMTV-PyMT breast cancer mouse model, associating increased Runx1 expression with tumor progression, whilst Runx1 upregulation was associated with radiation-induced mammary tumors in rats." (PMID 36831308, 2023). "Among the different types of cancers, mis-regulation of RUNX1 is associated with female-related cancers such as breast cancer, uterine cancer, and ovarian cancer." (PMID 36430923, 2022). "In clinical studies, ~10% of AML patients were identified to have translocations near the RUNX1 chromosomal region, ~7% of esophageal cancer patients had RUNX1 deletion mutations, and ~4% of breast cancer patients had RUNX1 inactivating mutations." (PMID 36429115, 2022). "For example, in breast cancers, the loss of RUNX1 in estrogen receptor-positive mammary epithelial cells increases β-catenin signaling and stimulates cell proliferation." (PMID 36430923, 2022). "Through analysis of the TIMER database, we found that RUNX1 had highly frequent mutations in breast cancer, while RUNX2 and RUNX3 had a lower frequency of mutation rate." (PMID 34485309, 2021). "Albeit with a lower frequency, mutations in RUNX1 are also found in solid malignancies, such as breast cancer." (PMID 34638295, 2021). "We also found that RUNX1 mutations in breast cancer significantly increased the infiltration of CD8+T cells, CD4+T cells, and macrophages in breast cancer." (PMID 34485309, 2021). "Missense mutations of RUNX1 were reported in luminal-type breast cancer, and loss-of-function somatic mutations or deletion of RUNX1 have been reported in breast cancer and lung cancer." (PMID 32498288, 2020). "The low RUNX1 expression in breast cancers is associated with metastasis to lymph nodes and poor survival." (PMID 32498288, 2020). "RUNX1 loss promotes oestrogen receptor ER+ breast cancer epithelial cell growth and stem cell markers, but this growth promotion does not occur in ER- breast epithelial cell lines." (PMID 31370857, 2019). "Recurrent mutations in RUNX1 and its binding partner CBFβ were detected in two independent cohorts of breast cancer deep sequencing studies." (PMID 29581836, 2018). "Here we demonstrate the consequences of Runx1 loss in normal mammary epithelial and breast cancer cells." (PMID 28407681, 2017). "Significantly, we demonstrated that loss of Runx1 in luminal like breast cancer cells (MCF7) can promote EMT." (PMID 28407681, 2017).
breast cancer (continued). "We have further studied the consequence of disturbing normal Runx1 function in breast cancer cells and provided evidence that Runx1 loss of function has a significant effect on cancer-related mechanisms." (PMID 28407681, 2017). "The convergence of these multiple pathways that inhibit Runx1 expression leads us to conclude that loss of Runx1 is an important mechanistic step in breast cancer initiation and/or progression." (PMID 28407681, 2017). "Taken together, these biochemical and clinical data support the emerging concept that Runx1 is a tumor suppressor and that loss of Runx1 is associated with the progression of breast cancer." (PMID 28407681, 2017). "Recent genetic studies have identified loss-of-function somatic mutations or deletion of Runx1 in breast cancer patients." (PMID 28407681, 2017). "Our identification of TGFβ as a Runx1 upstream regulator provides insight into the compromised mechanisms of Runx1 function that are associated with breast cancer." (PMID 28407681, 2017). "Recently, mutations of transcription factor CBFB and deletions of RUNX1 causing Runx1/Cbfb complex loss of function in breast cancer has been identified by whole-genome sequencing." (PMID 29245924, 2017). "It suggests that loss of RUNX1 in breast cancer facilitates ERα-mediated suppression of AXIN1, resulting in aberrant β-catenin signalling." (PMID 26916619, 2016). "Recent high-throughput studies revealed recurrent RUNX1 mutations in breast cancer, specifically in oestrogen receptor-positive (ER+) tumours." (PMID 26916619, 2016). "Our work marks AXIN1 as a potential therapeutic target to remedy deregulation of β-catenin in ER+ breast cancer tumours that have lost RUNX1 function through somatic mutations or other mechanisms." (PMID 26916619, 2016). "On the other hand, large-scale sequencing studies in human breast cancer revealed frequent RUNX1 mutations and deletions." (PMID 26735887, 2016). "Previously, several studies have suggested that the RUNX1 gene is highly expressed in breast epithelial cells and it is frequently mutated in breast cancer." (PMID 26920143, 2016). "The CBFB mutations were found to be accompanied by deletions of the gene encoding its binding partner, RUNX1, in some breast cancers." (PMID 26870154, 2015). "The RUNX1 mutations identified from the recent sequencing studies ofhuman breast cancers include point mutations, frame-shift mutations, and deletions." (PMID 25415051, 2014). "From recent whole-genome/exome sequencing studies, RUNX1 andCBFB mutations were only identified in the luminal subtype ofhuman breast cancers, which are typicallyER+." (PMID 25415051, 2014). "The next challenge is to determine exactly how RUNX1 mutations work together with theloss of the tumor-suppressing protein to drive breast cancer development." (PMID 25415051, 2014). "In particular, RUNX1 seems to play an important role in breast acinar morphogenesis, and is frequently downregulated or mutated in breast cancer." (PMID 23344057, 2013). "Current evidence indicates that RUNX1 and CBFβ are among the 30 most frequently mutated genes in breast cancer, with a prevalence of approximately 4%–5% in breast cancer cases." (PMID 40614729, 2025). "Both RUNX1 and CBFβ are in the top 30 genes mutated in breast cancer." (PMID 40614729, 2025). "Together, these observations suggest that IPA-mediated disruption of RUNX1 introduces previously unrecognized pathogenic mechanisms that may contribute to breast cancer progression." (PMID 41218079, 2025). "Further examination of this co-occurring mutation across all cancer studies on cBioPortal showed that this mutational relationship between DDR1 and either RUNX1 or CBFβ remained strongly significant, indicating that this axis is worth investigating outside of breast cancer." (PMID 40614729, 2025).